TLR2 (toll like receptor 2)
Diseases named in the same sentence as TLR2 in open-access papers (continued):
Sharing a sentence is not in itself a finding about the gene and the disease.
Acute hepatic failure (1 paper, 2022). Hepatic failure refers to the inability of the liver to perform its normal synthetic and metabolic functions, which can result in coagulopathy and alteration in the mental status of a previously healthy individual. "The most prominent hepatic TLRs are TLR2 and TLR4 have been shown to be important for the production of the inflammatory response observed in different models of experimental hepatic injury such as hepatic ischemia, inflammation, and acute hepatic failure." (PMID 35517830, 2022).
Acute otitis media (1 paper, 2012). Acute otitis media is a short and generally painful infection of the middle ear. "In contrast, the TLR2-mediated immune response is significantly involved in S. pneumoniae-induced acute otitis media." (PMID 22539951, 2012). "Tlr2-/- mice are more vulnerable to the challenge of gram-positive bacterium S. pneumoniae because of impaired bacterial clearance ability that leads to acute otitis media in this model." (PMID 22539951, 2012).
adult-onset Still disease (1 paper, 2022). A rare inflammatory multisystem disorder characterized clinically by fever of unknown origin, arthralgia or arthritis, hyperleucocytosis, and typical skin rash. "This study investigated the role of Toll-like receptor 1 (TLR1), TLR2, TLR4, TLR7, and TLR9 in patients with adult-onset Still’s disease (AOSD)." (PMID 35715478, 2022).
age-related macular degeneration (1 paper, 2014). Age-related loss of vision in the central portion of the retina (macula), secondary to retinal degeneration. "Proteins that are post-translationally adducted with 2-(ω-carboxyethyl)pyrrole (CEP) have been proposed to play a pathogenic role in age-related macular degeneration, by inducing angiogenesis in a Toll Like Receptor 2 (TLR2)-dependent manner." (PMID 25343517, 2014).
alcoholic liver cirrhosis (1 paper, 2013). A disorder of the liver characterized by the presence of fibrotic scar tissue instead of healthy liver tissue. "In contrast to sera from healthy controls, sera from patients with alcoholic cirrhosis induced CXCL1 secretion in TLR2- (p=0.016) and TLR4- (p=0.008) transfected HEK293 cells." (PMID 24260493, 2013).
ameloblastoma (1 paper, 2020). The most common odontogenic tumor, arising from the epithelial component of the embryonic tooth and usually affecting the molar-ramus region of the mandible or maxilla. "The association of Toll‐like receptor 2 (TLR2) expression with the behavior of ameloblastoma cells is also discussed." (PMID 32096304, 2020). "Our data indicate the possibility that TLR2 would be a candidate molecule for developing a treatment for ameloblastoma." (PMID 32096304, 2020). "Our gene expression analyses clearly indicated the overexpression of TLR2 with a concomitant activation of the KRAS‐related oncogenic gene set in patients with ameloblastoma." (PMID 32096304, 2020). "Although use of only single cell line AMU‐AM1, our finding that TLR2 knockdown suppresses KRAS‐related signaling and immune responses in AMU‐AM1 cells strongly indicates the possibility that TLR2 plays a pivotal role in ameloblastoma." (PMID 32096304, 2020). "To clarify the role of TLR2 in ameloblastoma cells, we examined the effect of TLR2 agonist Pam3CSK4 on the cellular signaling in AMU‐AM1 cells." (PMID 32096304, 2020). "We also found that TLR2 is highly expressed in ameloblastoma and may mediate both survival and inflammatory signaling in ameloblastoma cells." (PMID 32096304, 2020). "Since TLR2 is highly expressed in ameloblastoma tumors and AMU‐AM1 cells, which are derived from patients with recurrent ameloblastoma, it would be of particular interest to examine the association of the level of TLR2 expression with ameloblastoma malignancy." (PMID 32096304, 2020). "Collectively, these results suggest that TLR2 signaling may mediate cell survival signaling in ameloblastoma cells." (PMID 32096304, 2020). "In addition, Toll‐like receptor 2 (TLR2) knockdown readily inactivated KRAS‐responsive gene sets as well as increases caspase activities, suggesting that TLR2 signaling may mediate cell survival signaling in ameloblastoma cells." (PMID 32096304, 2020). "We found that TLR2, a gene involved in KRAS signaling, was listed as a top‐ranking upregulated gene in the ameloblastoma group." (PMID 32096304, 2020). "Accordingly, western blot analysis showed that protein expression levels of IGF‐II, TLR2, and INHBA were significantly increased in the ameloblastoma tumors compared to normal tissues." (PMID 32096304, 2020). "Moreover, our qRT‐PCR analysis, as well as microarray data, showed that mRNA expression levels of INHBA, IGF2, and TLR2, all of which are classified into the KRAS‐responsive gene sets, significantly increase in ameloblastoma compared to normal counterpart tissues." (PMID 32096304, 2020). "Although our data does not always show the role of TLR2 in cell growth of ameloblastoma, TLR2 may proactively function in ameloblastoma cells." (PMID 32096304, 2020).
ankylosing spondylitis (1 paper, 2005). An autoimmune chronic inflammatory disorder characterized by inflammation in the vertebral joints of the spine and sacroiliac joints. "In ankylosing spondylitis, TLR4 (23.1 ± 21.9%) and, to a smaller extent, TLR2 (4.1 ± 5.8%) were expressed on CD4+CD28null T cells, whereas expression was negligible on CD4+CD28+ and CD8+ T cells." (PMID 16277694, 2005).
aortic aneurysm (1 paper, 2020). A ruptured aneurysm located in the wall of the proximal portion of the descending aorta proceeding from the arch of the aorta. "For example, TLR2 has been shown to regulate Ang II-induced inflammatory responses in heart and kidney tissues, and during aortic aneurysms and aortic stenosis." (PMID 33318302, 2020). "Furthermore, miR-144-5p was found to regulate TLR2 signaling and the progression of aortic aneurysms following Ang II administration in apolipoprotein E knockout mice." (PMID 33318302, 2020).
aortic atherosclerosis (1 paper, 2023). A atherosclerosis that involves the aorta. "A multi-TLR inhibitor, soluble TLR2, abrogated chronic vascular inflammatory responses and the increased aortic atherosclerosis-associated gene expression observed in nephropathic mice, without compromising infection clearance." (PMID 37849759, 2023).
arenavirus infection (1 paper, 2012). "With the identification of TLR2 as a mediator of proinflammatory responses to arenavirus infection, a closer investigation into the role of TLR2 in arenavirus pathogenesis is warranted." (PMID 23202459, 2012). "Along with the global effects of TLR2 signaling in arenavirus infection, it is still necessary to determine how arenaviruses stimulate the TLR2-dependent response and how this is inhibited during pathogenic arenavirus infection." (PMID 23202459, 2012). "The mechanism by which TLR2-dependent cytokine responses are induced during arenavirus infection, and conversely, how those responses are inhibited are unclear." (PMID 23202459, 2012). "Two important questions remain: how does TLR2 signaling contribute to resistance/recovery from arenavirus infection and how could the virus inhibit TLR2 signaling?" (PMID 23202459, 2012).
ascariasis (1 paper, 2021). An infection that is caused by the roundworm Ascaris lumbricoides, many cases of which remain asymptomatic. "This study showed that one of the resistance mechanisms against ascariasis is dependent on TLR2 and TLR4 signaling and the presence of eosinophils, which results in SIgA production." (PMID 34784389, 2021). "Furthermore, we highlight the importance of TLR2 and TLR4 receptor signaling in eosinophil recruitment and SIgA production, resulting in effective cellular and humoral immune responses against larval ascariasis in mice." (PMID 34784389, 2021).
Ascites (1 paper, 2012). Accumulation of fluid in the peritoneal cavity (between the layers of the peritoneum that lines the abdomen). "According to one study, cirrhotic patients with ascites had an increased risk of developing SBP in the presence of a specific TLR2 genotype (16934 TT genotype) or a TLR2 GT microsatellite polymorphism; presence of both risk factors further augmented the susceptibility for SBP." (PMID 23087650, 2012).
aspiration pneumonia (1 paper, 2020). "Our results suggest that P. gingivalis is a powerful inflammatory stimulant for human bronchial and pharyngeal epithelial cells and can stimulate TLR2-mediated cytokine production, thereby potentially contributing to the onset of aspiration pneumonia." (PMID 33114582, 2020).
Azoospermia (1 paper, 2017). Absence of any measurable level of sperm,whereby spermatozoa cannot be observed even after centrifugation of the semen pellet. "This study was conducted to investigate the expression of TLR2 andTLR3 in Sertoli cells of men with azoospermia." (PMID 28836400, 2017).
B cell lymphopenia (1 paper, 2018). "Increased numbers of peripheral Th17 cells, B cell lymphopenia, and lower TLR2 expression in monocytes, as well as the use of cyclophosphamide were the major risk factors for the development of infection and thus were included in the index." (PMID 30692998, 2018).
bancroftian filariasis (1 paper, 2021). "TLR2 polymorphisms were shown to be associated with bancroftian filariasis." (PMID 34566972, 2021).
Barrett’s metaplasia (1 paper, 2021). "In addition to downstream proinflammatory effects, TLR2 stimulation was shown to improve mucosal integrity and epithelial barrier preservation in oesophageal squamous epithelium, in ex vivo and in vitro model intestinal epithelial cell lines and in Barrett’s oesophagus." (PMID 33686512, 2021). "We have previously shown that both TLR2 and TLR4 were expressed in normal squamocellular oesophageal epithelium, and expression increased in Barrett’s metaplasia-dysplasia-adenocarcinoma sequence, but their participation in oesophageal inflammation is unconfirmed." (PMID 33686512, 2021).
Bartonella infections (1 paper, 2025). "Previous studies have revealed that specific sites on TLR1, TLR2, and TLR5 genes were significantly associated with the risk of Bartonella infection." (PMID 40678527, 2025). "In this study, we analyzed the polymorphisms in six cell surface TLR genes (TLR1, TLR2, TLR4, TLR5, TLR6, and TLR10) in striped hamsters, aiming to determine their association with Bartonella infections and ectoparasite parasitism, including fleas and gamasid mites." (PMID 40678527, 2025).
bone marrow failure (1 paper, 2021). "Here, we demonstrate that lymph node (LN) cells from B6-based donor mice carrying IL-6, TLR2, or TLR4 gene deletions were fully functional in inducing severe pancytopenia and bone marrow failure (BMF) when infused into MHC-mismatched CByB6F1 recipients." (PMID 33711076, 2021).
bovine tuberculosis (1 paper, 2016). "The present study was aimed at exploring the association of seven single nucleotide polymorphisms (SNPs) in TLR2 and TLR4 genes with susceptibility/resistance against bovine tuberculosis (bTB) infection in cattle." (PMID 27284220, 2016).
Brain atrophy (1 paper, 2019). Partial or complete wasting (loss) of brain tissue that was once present. "Our data indicate that the genomic deletion of TLR2 impairs neurobehavioral functions, induces WMD and brain atrophy, and increases the activation of astrocytes, which in turn aggravate the symptoms of AD through a non-Aβ mechanism." (PMID 31509519, 2019).
carcinoma in situ (1 paper, 2010). "In fact, histological analysis revealed almost twice the incidence of advanced carcinoma in situ (0.3 vs 0.6 mean carcinoma in situ per mouse) in TLR2−/−mice as compared to WT, which trended towards significance (p<0.055)." (PMID 20885960, 2010).
carotid atherosclerosis (1 paper, 2022). A thickening and loss of elasticity of the walls of carotid arteries that occur with formation of atherosclerotic plaques. "Interestingly, recent immunofluorescence experiments revealed colocalization of PAR1 with toll-like receptors (TLRs)—TLR2 and TLR4—in human carotid atherosclerotic lesions, pointing to activation of TLRs and interaction with PAR1 in an innate immune response in carotid atherosclerosis." (PMID 35742805, 2022).
central nervous system infections (1 paper, 2024). "In bacterial and viral central nervous system infections, the participation of receptors TLR2 and TLR4 has been documented." (PMID 39553478, 2024).
cerebral toxoplasmosis (1 paper, 2019). Infections of the brain caused by the protozoan toxoplasma gondii that primarily arise in individuals with immunologic deficiency syndromes (see also aids-related opportunistic infections). "Further studies using a better model, for example mice with a conditional deletion of TLR2 in their microglial cells and astrocytes or identification of the TLR2 ligand in T. gondii should extend our understanding of the role of TLR2 in cerebral toxoplasmosis." (PMID 31404078, 2019).
Chagas cardiomyopathy (1 paper, 2018). A disease of the cardiac muscle developed subsequent to the initial protozoan infection by trypanosoma cruzi. "Furthermore, TLR-2 and TLR-4 expression are associated with the production of pro-inflammatory cytokines in Chagas’ cardiomyopathy, while in asymptomatic patients these receptors as predominantly associated with IL-10 and TGF-β production." (PMID 29599775, 2018).
cholangitis (1 paper, 2022). An acute or chronic inflammatory process affecting the biliary tract. "Toll-like receptor 2 (TLR2)–deficient dnTGFβRII mice showed a more severe cholangitis activity correlated with disrupted epithelial barrier integrity." (PMID 35536431, 2022).
choroidal neovascularization (1 paper, 2016). An eye disorder described by the growth of new blood vessels that originate from the choroid through a break in the Bruch membrane into the sub–retinal pigment epithelium (sub-RPE) or subretinal space. "Moreover, increased VEGF‐A expression specifically in the RPE was sufficient to cause choroidal neovascularization (CNV) as in neovascular AMD, which could be inhibited by RPE‐specific inactivation of Flk1, while Tlr2 inactivation strongly reduced CNV." (PMID 26912740, 2016).
chronic autoimmune hepatitis (1 paper, 2023). "Recent studies showed that TLR2/4-mediated inflammasome activation in CD14+ monocytes was critical to maintaining dysfunctional Tregs in de novo autoimmune hepatitis." (PMID 36778150, 2023). "M2 macrophages were dominant during early stages of immune responses, while TLR4 continued to express highly and expression of TLR2 was decreased, which would resulted in polarization of liver resident macrophages from M2 to M1 to promote the development of chronic autoimmune hepatitis." (PMID 36778150, 2023). "TLR2 and TLR4 ligands mediated liver resident macrophages polarization to favor chronic autoimmune hepatitis development." (PMID 36778150, 2023). "One potential reason for this result may be that TLR2 and TLR4 ligands regulate macrophage polarization to promote autoimmune hepatitis progression." (PMID 36778150, 2023). "In conclusion, this study showed that TLR2 and TLR4 ligands could regulate liver resident macrophages polarization to favor chronic autoimmune hepatitis development." (PMID 36778150, 2023).
chronic endometritis (1 paper, 2016). A non-granulomatous or granulomatous chronic inflammation of the endometrium. "For this aim, expression of mRNAs for Toll-like Receptor 2 and 4 (TLR 2/4), interleukin 1β (IL-1β), interleukin 6 (IL-6) and tumor necrosis factor α (TNF) was examined in control mares versus either mares suffering from chronic endometritis (ChE) or subacute suppurative endometritis (SSE)." (PMID 27152525, 2016).
chronic pancreatitis (1 paper, 2016). A chronic inflammatory process causing damage and fibrosis of the pancreatic parenchyma. "Additionally, TLR2 and -4 gene expression was not significantly increased in tissue of chronic pancreatitis compared to normal tissue (TLR2 FD = 2.0 and TLR4 FD = 2.2, respectively)." (PMID 27941651, 2016).
clonorchiasis (1 paper, 2020). Infection of the biliary passages with clonorchis sinensis, also called Opisthorchis sinensis. "In our previous study, we showed dramatic changes of TLR2 and TLR4, and production of IFN-γ, IL-6, TNF-α, and IL-10 in the spleen were regulated by TLR4 as demonstrated in a murine model of clonorchiasis using TLR4 defective mice." (PMID 33489026, 2020).
cocaine use disorder (1 paper, 2021). A substance-related disorder that involves the recurring use of cocaine despite negative consequences. "Further studies are needed to assess whether Ex4 can exert neuroprotective effects for treating cocaine use disorder by blocking TLR3 and TLR2 signaling or through other factors." (PMID 34349653, 2021).
colonic disease (1 paper, 2015). "Importantly, we have shown that RA is capable of inhibiting colonic disease and this is dependent upon TLR2 as seen by decreased pro-inflammatory cytokine production, better histology scores and less bleeding." (PMID 25826367, 2015).
colorectal polyps (1 paper, 2020). "We also found that intestinal TLR2, 3, 4, and 5 expression levels were associated with location, size, and dysplasia grade of different types of colorectal polyps." (PMID 33255933, 2020). "A significant association between TLR2 and TLR4 expression levels and location of colorectal polyps was observed." (PMID 33255933, 2020). "In addition, we found that intestinal TLR2, 3, 4, and 5 expression levels associate with location, size, and dysplasia grade of colorectal polyps and their expression levels may play important roles in the development of site-specific histological types of colorectal polyps." (PMID 33255933, 2020). "The noteworthy point was that the RQs of TLR2, TLR3, TLR4, and TLR5 were significantly different among histologically different colorectal polyp types compared to samples from normal participants (p-value < 0.001)." (PMID 33255933, 2020). "The aim of our study was to evaluate the expression levels of TLR2, TLR3, TLR4, and TLR5 in intestinal biopsy specimens of patients with different histological colorectal polyp types including HP, SSA, tubular adenoma (TA), and villous/tubulovillous (VP/TVP) cases compared to normal controls." (PMID 33255933, 2020).
common variable immunodeficiency (1 paper, 2023). "In this study, we aim to unravel the intricate involvement of TLR2, TLR4, TLR3, TLR7, TLR8, and TLR9 in the immunopathogenesis of common variable immunodeficiency—CVID (as PID)—and chronic lymphocytic leukemia—CLL (as SID)." (PMID 37626865, 2023).
congenital syphilis (1 paper, 2024). A life-threatening bacterial infection of the newborn caused by Treponema pallidum. "TLR2 is a receptor for Treponema pallidum, which causes congenital syphilis." (PMID 38775708, 2024).
coronary artery stenosis (1 paper, 2011). "Supporting the role of TLR2 and TLR4, response for peripheral blood monocytes to TLR2 and TLR4 ligands was significantly associated with the degree of coronary artery stenosis." (PMID 21698167, 2011).
crescentic glomerulonephritis (1 paper, 2014). A histopathologic term for a pattern of diseases characterized by extensive crescent formation in the glomeruli; patients present clinically with rapid deterioration of renal function, and possible progression to end-stage renal failure within weeks or months. "This indicated that the TLR2 signaling pathway was involved in crescentic glomerulonephritis." (PMID 24926370, 2014).
cutaneous sarcoidosis (1 paper, 2011). "However, in cutaneous sarcoidosis, rs3804099 and rs3804100 SNPs in TLR2 are slightly associated with clinical disease." (PMID 21437199, 2011). "The variants of the TLR2 gene in DDCs may play a causative role in the development of cutaneous sarcoidosis in a site-specific manner." (PMID 21437199, 2011).